RNU6-638P (RNA, U6 small nuclear 638, pseudogene)
Gene: Small nuclear RNA gene on chromosome 17 (78,696,694 to 78,696,797, reverse strand). Ensembl gene ENSG00000252391.
Homologues: Orthologues: chimpanzee U6 (99% identical), guinea pig RNU6-638P (89% identical), mouse Gm55574 (78% identical). Paralogues in human: RNU6-1145P (80% identical), RNU6-639P (80% identical), RNU6-1316P (78% identical), RNU6-188P (78% identical), RNU6-38P (78% identical), RNU6-669P (78% identical), RNU6-1214P (77% identical), RNU6-1290P (77% identical), RNU6-224P (77% identical), RNU6-477P (77% identical), RNU6-836P (77% identical), RNU6-20P (76% identical), and 1285 more.